EGFR (epidermal growth factor receptor)
Diseases named in the same sentence as EGFR in open-access papers (continued):
Sharing a sentence is not in itself a finding about the gene and the disease.
tumor (continued). "In this regard, one of the main reasons for therapeutic resistance in GBM is due to the proliferative and highly invasive nature of GBM tumours, which can be attributed to cellular plasticity and the dynamic changes in expression and signalling of EGFR." (PMID 36497413, 2022). "Such PET tracers can be used to predict whole-body and tumor drug uptake and thereby guide EGFR-TKI drug treatment." (PMID 35890095, 2022). "Two other pathways were similarly expressed in primary cell cultures and in tumor tissue of origin, and these hold crucial implications: The EGFR tyrosine kinase resistance pathway as well as well as the PD-1 pathway." (PMID 35646693, 2022). "There are two basic techniques to combine chemotherapeutic agent toxicity and the precise targeting of EGFR overexpressing tumor tissues: antibody–drug conjugates (ADCs) and antibody–nanoparticle conjugates (ANCs)." (PMID 35409206, 2022). "Due to poorly understood mechanisms, the heterogeneity of the tumor can allow the cells to reversibly increase or decrease their level of EGFR vIII expression, maximizing their growth potential." (PMID 36199696, 2022). "First, we sorted high EGFR+ tumor cells by fluorescence-activated cell sorting to eliminate fibroblasts and enrich for tumorigenic cells." (PMID 35902768, 2022). "Generally, in the dose expansion cohorts of TATTON trial, savolitinib plus osimertinib showed promising anti-tumor activity in MET-amplified EGFR positive advanced NSCLC patients who received a prior third-generation EGFR–TKI." (PMID 36551608, 2022). "On the other hand, a previous study has demonstrated that Se/FO can enhance the anticancer activity of bevacizumab by inhibiting tumor EGFR, TβR, and AXL proteins in breast tumor-bearing mice." (PMID 36547898, 2022). "To investigate potential mechanisms of how the modulation of oncogenic EGFR signalling in tumour cells facilitates changes in the immune response, we next examined the expression of the transcription factor, IRF1, a known tumour suppressor gene." (PMID 36010935, 2022). "The diversity of EGFR-TKI resistance mechanisms and tumor evolution during long-term EGFR-TKI therapy complicates efforts to manage EGFR-TKI-resistant tumors after EGFR-TKI resistance develops." (PMID 36612121, 2022). "Increased EGFR expression is thus expected to be a powerful prognostic factor in a variety of tumour forms and blocking its cellular functions looks to have significant therapeutic effects." (PMID 35801486, 2022). "The SPECT/CT imaging of the subcutaneous tumors demonstrated significantly increased radioactivity accumulation in the MGC803 tumor (high EGFR expression) than in the HT29 tumor (low EGFR expression) (T/M: 3.21 ± 0.27 vs. 1.09 ± 0.07, P < 0.05)." (PMID 35903247, 2022). "During tumorigenesis, EMT induces tumor cells to increase their invasive capability and resistance to therapeutic regimens, including chemotherapy and EGFR TKIs." (PMID 36139582, 2022). "Cellular EGFR expression, tumor cell density, plasma antibody concentration, and delivery barrier were independently associated with local intratumoral panitumumab-IRDye800 concentration, with 0.62 goodness of fit of prediction." (PMID 35332092, 2022). "To demonstrate that the CPT11-loaded liposome targets EGFR overexpressed tumor cells, we performed western blotting analysis on four different CRC cell lines, including CW-2, LoVo, SW620 and CT116 cells." (PMID 35918704, 2022). "In glioma cells, upon EGFR activation, Fyn is activated causing the phosphorylation of G6PD at Tyr481, leading to enhanced PPP activity, tumour growth and radiation resistance." (PMID 36217026, 2022).
tumor (continued). "In this study, we employ multi-omics approaches based on bulk and single-cell transcriptomic datasets to investigate the role of MAP2K1, mTOR, YAP1 and EGFR in the tumor immune context of tumor microenvironment." (PMID 35655775, 2022). "It is worth mentioning that knocking down ARF6 also disrupted the PM localization of EGFR mutants and inhibited the growth of tumor cells." (PMID 36224181, 2022). "EGFR inhibitor significantly decreased tumor ability of proliferation, migration and invasion, rescued by upregulation of endogenous SPINK1." (PMID 36053457, 2022). "The application of RS-EPI DWI to predict aggressive features, such as the status of EGFR and tumour differentiation, in RC has been reported in a limited number of previous studies." (PMID 36505889, 2022). "As previously reported, tumor regions in the brain consisting of Nluc-H1915 cells were identified as EGFR+ areas by IHC staining." (PMID 34797455, 2022). "Gefitinib and SAHA monotherapy led to only a slight reduction in tumor volume, while co-administration of SAHA with EGFR-TKI resulted in significant tumor shrinkage." (PMID 35402377, 2022). "EGFR also modulates tumor survival and angiogenesis, and EGF-induced STAT3 signaling initiates the transcription of genes that modulate cell growth, survival, and angiogenesis (Cyclyn D1, Bcl-XL, and VEGF, respectively)." (PMID 35200568, 2022). "We found that EGFR inhibition mediated a higher infiltration of immune cells and increased local proliferation of T-cells in the tumours." (PMID 36010935, 2022). "The ErbB family of receptor tyrosine kinase (RTK) includes EGFR, ERBB2, ERBB3 and ERBB4, which were frequently associated with malignant proliferation of tumor cells." (PMID 35551652, 2022). "The best studied tumor-specific antigen is EGFRvIII, which is a constitutively active mutant form of EGFR only expressed in 25–30% of GBM." (PMID 35428347, 2022). "Some studies have used bivalent anti-EGFR Nb coupled with pseudomonas exotoxin (PE) to potentiate killing of GB tumor cells and tumor stem cells by pro−apoptotic tumor necrosis factor−related apoptosis−inducing ligand (TRAIL)." (PMID 36426363, 2022). "Genetic changes linked with tumor include alterations in isocratic dehydrogenase (IDH), changes in epidermal growth factor receptor, platelet-derived growth factor receptor changes, aberrant epigenetic changes, and loss of heterozygosity of 1p/19q." (PMID 36185622, 2022). "Recently, we have shown that nanoMIPs can bind specifically tumour cells by interacting with membrane protein receptors, such as EGFR." (PMID 36365575, 2022). "The first involves attenuated phosphorylation of HER2 and EGFR and regressed activation of downstream signaling relevant to tumor growth." (PMID 36090218, 2022). "More precisely, results from the EURTAC trial correlated EGFR mutations in cfDNA with OS, PFS, and treatment response and proved the feasibility of using cfDNA instead of tumor biopsy during treatment with erlotinib." (PMID 36139444, 2022). "EGFR Fab ́ conjugated nanoparticles enhanced tumor tissue uptake in SMMC-7721 tumor bearing mice when compared to non-modified nanoparticles." (PMID 35248080, 2022). "Knocking down ARF6 blocks EGFR sorting to PM, causes degradation of EGFR, disrupts EGF-induced EGFR signaling, and inhibits the growth of EGFR-overexpression tumor cells." (PMID 36224181, 2022). "Preclinical studies have reported that osimertinib is effective in EGFR ex20ins mutant cell lines and tumor xenografts with a wide therapeutic window." (PMID 35418149, 2022). "Cetuximab and panitumumab competitively inhibit epidermal growth factor binding, preventing the growth and survival of EGFR-expressing tumor cells." (PMID 35685436, 2022).
tumor (continued). "EGFR plays a fundamental role in the regulation of cell proliferation, migration, differentiation, and survival, and the deregulation of EGFR leads to enhanced signaling activity that promotes tumor proliferation, invasion, angiogenesis, and metastasis." (PMID 35056800, 2022). "DdPCR targeting KRAS Q61H in H460 xenografted mice and EGFR T790M mutation in H1975 xenografted mice, identified a variation of ctDNA detection at similar tumor size, suggesting that the amount of ctDNA released during tumor growth may be specific to each cell line." (PMID 35628154, 2022). "Another major cell-autonomous component of tumor progression, EGFR, was shown to drive basal expression of NKG2D ligands in epithelial cancer cells." (PMID 35967396, 2022). "Suppressing PGM3 reduces protein glycosylation, causes a sustained unfolded protein response, downregulates the pro-tumor EGFR-Akt axis, and ultimately leads to cell death." (PMID 36699061, 2022). "CXCL10 siRNA treatment of EGFR-mutant tumor cells also decreased CXCL10 in the supernatant from coculturing with activated PBMCs, suggesting that the effects of CXCL10 occur via autocrine and paracrine pathways." (PMID 36612121, 2022). "This combination enhanced attenuation of the PI3K/Akt/mTOR pathway more than EGFR inhibitor alone, including enhancing the tumour cell killing effect, which is unsurprising given the positive role of CK2 in phosphorylating prosurvival Akt." (PMID 35214064, 2022). "EGFR is a cell membrane growth factor receptor and is reported to be overexpressed in several types of tumor." (PMID 35631335, 2022). "These aspects should be taken into consideration when evaluating and comparing previous findings on the effect of ICB and targeted therapy on EGFR-driven tumours and the TME." (PMID 36010935, 2022). "Targeted therapies, including monocolonal antibodies against VEGF (bevacizumab) or EGFR (cetuximab or panitumumab) are used in the metastatic setting in combination with chemotherapy depending on RAS mutational status and tumor location (left vs. right)." (PMID 35565237, 2022). "Subsequent HIF-2α inhibition with concomitant EGFR inhibition and ionizing radiation led to radiosensitization and a significant decrease in tumor growth." (PMID 35409179, 2022). "As shown by tumor spheroid formation assay and colony formation assay, silence of EGFR in MDA-MB-231 exhibited limited tumor initiating capacity when treated with erastin." (PMID 35725558, 2022). "EGFR-targeting panitumumab-modified PEG NPs acting on the HCT 116 mouse model deliver oxaliplatin specifically to the tumor site." (PMID 35953863, 2022). "During treatment with gefitinib, there is a significant positive correlation between the tumor size and urine DNA content in the EGFR-positive patients." (PMID 35651679, 2022). "An in vivo tumor xenograft study using athymic nude mice was performed to determine antitumor activity of two formats of anti-EGFR/PD-L1 BsAbs compared to parental mAbs." (PMID 35890277, 2022). "To further dissect the impact of differential Ptp10D and EGFR recycling in tumor-suppressive cell competition, we selectively blocked retromer function with Vps26 RNAi or SNX27 RNAi in scrib mutant clones." (PMID 36271083, 2022). "So, cet.Hum.scFv molecules should disappear in blood stream sooner than cetuximab, while still presenting in tumor tissues, where tumor cells with higher EGFR expression are present." (PMID 35517713, 2022). "Another anti-ADAM17 monoclonal antibody, MEDI3622, inhibits tumor-dependent EGFR activity with IC50 values of 39 pmol/L and 132 pmol/L against human and murine ADAM17, respectively." (PMID 36466812, 2022).
tumor (continued). "One of the most studied is the epidermal growth factor receptor (EGFR), a transmembrane tyrosine kinase receptor of the ErbB family that promotes multiple signaling pathways involved in tumor cell growth, evasion, angiogenesis, and invasion." (PMID 35052649, 2022). "Greater infiltration of T-cells in general, as well as CD8+ T-cells and B cells, in the TME upon EGFR inhibition was further observed in immunohistochemistry staining of tumour sections from samples treated with either erlotinib or aPD-1 + erlotinib." (PMID 36010935, 2022). "The concept of the present investigation was to identify curcumin derivatives with better binding affinities to EGFR and NF-κB to improve tumor specificity and reduce side effects on normal organs." (PMID 35409325, 2022). "Only combined inhibitions of the EGFR signalling and the eHsp90α autocrine signalling led to the full blockade of the tumour cell migration as the LRP-1 depletion did." (PMID 35835845, 2022). "In our experiments, CRNDE was upregulated in HCC tumor specimens and induced elevation of EGFR expression, thereby increasing proliferation and sorafenib resistance." (PMID 35999564, 2022). "When the C797S mutation occurs, the osimertinib binding efficiency decreases, resulting in tumor resistance to all third-generation EGFR-TKIs." (PMID 35840984, 2022). "It is also an appealing target for tumor imaging, and EGFR antibodies and antibody fragments have been the subject of radionuclide studies." (PMID 35053365, 2022). "The live-animal IVIS imaging at 24 h demonstrated that the bioluminescent FLuc (tumor) and fluorescent Cy5.5 (mAb) overlapped in the brain, which suggested that the EGFR mAb penetrated the BBB and accumulated in the GBM xenograft." (PMID 35052809, 2022). "Both EGFR and c-Met are tumor metastasis-related receptors that are involved in the regulation of tumor cell metastasis, and have been extensively studied." (PMID 35538033, 2022). "In this study, we developed a PBPK model reflecting the essential features of tissue distribution of EGFR-TKIs with the primary aim to predict the image quality by predicting the right tumor-to-lung contrast." (PMID 35890095, 2022). "This preliminary study compares the anticancer efficacy of EGFR-TKIs (gefitinib or erlotinib) in Lewis LLC1 tumor-bearing mice when administered alone or in combination with Se and FO." (PMID 36547898, 2022). "Epidermal growth factor receptor (EGFR) pathway blocker was the top compound that enhanced T-cell killing of tumor cells in a high-throughput immune-oncology screen, possibly by stimulate the antigen presentation machinery and other mechanisms." (PMID 36443704, 2022). "The REG4 secreted by pancreatic cancer cells promoted macrophage polarization to M2 via EGFR/Akt/cAMP-responsive element binding activation, finally promoting tumor growth and distant metastasis." (PMID 36172286, 2022). "EGFR is a receptor tyrosine kinase, which can act as a regulator of tumor immune monitoring, activate the JAK/STAT3 signaling pathway, and promote the expression of PD-L1." (PMID 35707465, 2022). "Current National Comprehensive Cancer Network guidelines recommend the use of a fluoropyrimidine, with or without bevacizumab, or for patients with RAS/BRAF wild-type tumours and left-sided disease, an anti-EGFR antibody." (PMID 35440667, 2022). "HDAC inhibitors repress EGFR/EGFRvIII expression inducing the expression of FOXO1—a tumor suppressor—in MYC-driven medulloblastoma cells." (PMID 35785151, 2022). "Crosstalk between HIF and epidermal growth factor receptor (EGFR) has also been described as a tumor-promoting mechanism." (PMID 35912170, 2022). "The localized action of these products, within the timeframe of its effective retention in the microenvironment of the tumor tissue, will moderate EGFR-directed signaling in all resident cell types." (PMID 36232384, 2022).
tumor (continued). "The Raman dye 4-mercapto-hydroxybenzoic acid and polyethylene glycol were coupled with the tumor marker, epidermal growth factor receptor, to obtain the targeted SERS probes." (PMID 35684522, 2022). "As an important tumour driver gene, the epidermal growth factor receptor (EGFR) is involve in telomerase activity and enhances TERT transcription." (PMID 36420141, 2022). "For the EGFR-inhibited group, the afterglow signal was dimmer after 1 h post injection of cetuximab and reached a minimum at 2 h at the tumor site within the extended observation time window." (PMID 35105871, 2022). "Over the past few decades, with the in-depth study of tumor biology, an increasing number of molecular targets for drug therapy have been explored, including EGFR." (PMID 36482474, 2022). "The tumor-to-lung contrast for each EGFR TKI was predicted within the established boundaries, i.e., within threefold of the observed value." (PMID 35890095, 2022). "We compared the primary tumor resection (naive) to the resected relapse, which was treated with EGFR tyrosine kinase inhibitor lapatinib for 7–10 d before resection." (PMID 36123406, 2022). "In carcinomas, we reported that EGFR CAR T cells preferentially get activated in contact with tumor cells localized at the periphery of tumor islets." (PMID 36189315, 2022). "The inhibition of the tumor growth and the reduction of its related volume highlighted the fact that the EGFR-target liposome delivery system optimized the pharmacodynamics and pharmacokinetics of the CPT-11 drugs in CRCs." (PMID 35918704, 2022). "The application of anti-EGFR antibody cetuximab showed locoregional tumor control compared to radiotherapy alone." (PMID 35335158, 2022). "Comparison of miR profiles of EGFR-amplified and EGFR-normal GBM revealed an upregulation of the miR-183/96/182 cluster, which is associated with oncogenic properties in several tumor entities." (PMID 35486213, 2022). "Although ICI treatment in EGFR‐mutated NSCLC has been considered to have poor efficacy, efficacy tends to be better in patients with tumor L858R mutation." (PMID 34904383, 2022). "We anticipate that the majority of CTCs is detected using EpCAM and EGFR as tumor markers, combined with morphological confirmation." (PMID 36613466, 2022). "Genomic profiling based on a large sample has detected that EGFR alterations occur in almost every type of tumor, especially in more than half of GBMs." (PMID 35814475, 2022). "Indeed, poziotinib is also a potent inhibitor of wild-type EGFR, raising concerns that poziotinib may show a narrow therapeutic window, linked to insufficient therapeutic dosing due to toxicity and therefore contributing to short-term tumour responses." (PMID 35053553, 2022). "EGFR is overexpressed in tumor cells and has been the target of therapies against various types of cancer." (PMID 35326556, 2022). "Here, we found that fraction of CD24lowCD44high cells and size of tumor spheres clearly decreased following EGFR inhibition in TNBC cells." (PMID 35725558, 2022). "EGFR plays critical roles in many cellular processes, such as proliferation, migration, adhesion, as well as tumor growth." (PMID 35436989, 2022). "Traditionally, doctors identified the non-small cell lung cancer patients most likely to respond to EGFR inhibitors such as Iressa and Tarceva by taking and analyzing tumor samples." (PMID 36360466, 2022). "Overexpression of FUT6 inhibits the malignant activity of tumor cells by inhibiting the dimerization and phosphorylation of the epidermal growth factor receptor." (PMID 36510584, 2022). "Next, we verified the additive anti‐tumor effects of this combination in an EGFR mutant lung tumor syngeneic model." (PMID 35861366, 2022). "Considering that the phosphorylation of EGFR is an important intracellular signal that occurs during tumor progression, relating to the previous biological functions such as angiogenesis and the lipid metabolism in tumor, we focused on this signal pathway." (PMID 35237300, 2022).